ZBED4 (zinc finger BED-type containing 4)
Description:
Transcriptional regulator that binds to poly-guanine tracts in gene promoters and activates transcription (By similarity). Able to bind single- and double-stranded DNA and RNA (By similarity).
Synonyms: KIAA0637
Tractability: PROTAC: UniProt records ubiquitination sites on it; ubiquitination databases record sites on it.
Gene: Protein-coding gene on chromosome 22 (49,853,827 to 49,897,383, forward strand). Ensembl gene ENSG00000100426.
Subcellular location: Nucleus; Cytoplasm; Photoreceptor inner segment
Subcellular location (Human Protein Atlas): Nucleoplasm
Gene Ontology:
Molecular function: identical protein binding; protein binding; DNA-binding transcription activator activity, RNA polymerase II-specific; DNA-binding transcription factor activity, RNA polymerase II-specific; RNA binding; RNA polymerase II transcription regulatory region sequence-specific DNA binding; transcription cis-regulatory region binding; DNA binding; protein dimerization activity
Biological process: positive regulation of transcription by RNA polymerase II
Cellular component: cytoplasm; nucleoplasm; nucleus; photoreceptor inner segment; chromatin
Genetic constraint (gnomAD): Loss-of-function variants: 8 observed, 19.81 expected, observed/expected ratio (o/e) 0.4, 90% interval 0.24 to 0.73. The upper end of that interval is the gene's LOEUF score, 0.73, which puts it in group 2 of 6, group 1 being the genes least tolerant of losing a copy. Missense variants: 970 observed, 1,088 expected, observed/expected ratio (o/e) 0.89, 90% interval 0.85 to 0.94. Synonymous variants: 511 observed, 462.95 expected, observed/expected ratio (o/e) 1.1, 90% interval 1.03 to 1.19.
Homologues: Orthologues: chimpanzee ZBED4 (99% identical), macaque ZBED4 (98% identical), mouse Zbed4 (83% identical), rat Zbed4 (83% identical), dog ZBED4 (82% identical), guinea pig ZBED4 (79% identical), pig ZBED4 (71% identical), tropical clawed frog zbed4 (69% identical), zebrafish zbed4 (55% identical). Paralogues in human: ZBED6 (19% identical), ZBED1 (13% identical).
Diseases named in the same sentence as ZBED4 in open-access papers:
ZBED4 is named in the same sentence as 5 diseases in open-access papers, as found by Europe PMC text mining. Sharing a sentence is not in itself a finding about the gene and the disease. The quoted sentences say what the papers report.
retinoblastoma (2 papers, 2012 to 2015). A malignant tumor that originates in the nuclear layer of the retina. "Our results also demonstrate the nuclear and cytoplasmic co-localization of Zbed4 and ERα in Y79 retinoblastoma cells and they confirm the close association of these proteins." (PMID 22693546, 2012). "Our experiments also confirmed the nuclear co-localization and possible association of ZBED4 with SAFB1 and ERα and the cytoplasmic interaction of Zbed4 with MYH9 in Y79 retinoblastoma cells." (PMID 22693546, 2012). "The membrane overlay assay showed that after overlaying Zbed4 on the lane containing the separated proteins from Y79 retinoblastoma cells and probing the membrane with an ERα antibody, ERα was clearly detected (lane 5)." (PMID 22693546, 2012). "We also carried out co-immunoprecipitations using Y79 retinoblastoma cells’ nuclear extracts and antibodies against Zbed4 or SAFB1." (PMID 22693546, 2012). "We speculate that in Y79 retinoblastoma cells as well as in retina Zbed4 may be transported by the MYH9 trafficking system." (PMID 22693546, 2012). "Furthermore, immunocytochemistry showed that Zbed4 and ERα co-localize in both the nuclei and cytoplasm of Y79 retinoblastoma cells (Merged image)." (PMID 22693546, 2012). "We also found that Zbed4 interacts with nuclear and cytoplasmic proteins and corroborated these results by co-immunoprecipitating Zbed4 from Y79 retinoblastoma cells with the identified proteins, Scaffold Attachment Factor B1 (SAFB1), Estrogen Receptor alpha (ERα) and cellular Myosin 9 (MYH9)." (PMID 22693546, 2012). "We also found that Zbed4 interacts in Y79 retinoblastoma cells with nuclear and cytoplasmic proteins Scaffold Attachment Factor B1 (SAFB1), estrogen receptor alpha (ERα), and cellular myosin 9 (MYH9), as shown with immunoprecipitation and mass spectrometry studies as well as gel overlay assays." (PMID 22693546, 2012). "Zbed4 has been reported to interact with estrogen receptor alpha (ERα) and cellular myosin 9 (MYH9) in retinoblastoma cells." (PMID 25692136, 2015). "A reverse experiment using the same nuclear extract and the SAFB1 antibody also showed the presence of both Zbed4 and SAFB1 in the SAFB1 immunoprecipitate, corroborating their in vivo interaction in Y79 retinoblastoma cells." (PMID 22693546, 2012). "Moreover, Zbed4 and SAFB1 co-localized to the nuclei of Y79 retinoblastoma cells, providing further evidence of their interaction in vivo." (PMID 22693546, 2012). "To evaluate the in vivo interaction of native Zbed4 and SAFB1 proteins, we first used immuno-cytochemistry and confocal microscopy imaging to investigate whether they co-localized in Y79 retinoblastoma cells." (PMID 22693546, 2012).
schizophrenia (2 papers, 2021 to 2023). A major psychotic disorder characterized by abnormalities in the perception or expression of reality. "While MSANTD4 has been linked to Huntington’s disease, and ZBED4 has been linked to schizophrenia and Phelan-McDermid syndrome in recent studies, little is known about these proteins' underlying mechanisms." (PMID 37047316, 2023).
cancer (1 paper, 2025). A tumor composed of atypical neoplastic, often pleomorphic cells that invade other tissues. "Currently, no information is available on the role of IF rod domain-containing protein, NAC-A/B domain-containing protein, and ZBED4 in human and animal cancers." (PMID 40839607, 2025).
ZBED4 also shares sentences with these, for which no sentence is quoted: Huntington disease (1 paper); Phelan-McDermid syndrome (1).